COX6C (cytochrome c oxidase subunit 6C)
Diseases named in the same sentence as COX6C in open-access papers (continued):
Sharing a sentence is not in itself a finding about the gene and the disease.
Stroke (1 paper, 2024). Sudden impairment of blood flow to a part of the brain due to occlusion or rupture of an artery to the brain. "The main finding of this study is that the COX6C and NDUFB3 genes are highly expressed in septic shock and stroke, and the higher the expression of these genes, the worse the prognosis." (PMID 39655053, 2024). "The significant roles of COX6C and NDUFB3 genes in septic shock and stroke will be validated using public datasets." (PMID 39655053, 2024). "Core genes (UQCRQ, USMG5 [ATP5MD], COX6C, NDUFB3, ATP5L [ATP5MG], COX7C, NDUFA1, NDUFA4) were highly expressed in septic shock and stroke samples." (PMID 39655053, 2024). "COX6C and NDUFB3 are highly expressed in septic shock and stroke, and may play a significant role in the development of septic shock and stroke through cellular regulation and other pathways." (PMID 39655053, 2024). "However, the relationship between COX6C, NDUFB3 genes and septic shock and stroke is currently unclear." (PMID 39655053, 2024). "COX6C and NDUFB3 genes are highly expressed in septic shock and stroke." (PMID 39655053, 2024). "COX6C and NDUFB3 may serve as molecular targets for precise treatment of septic shock and stroke, providing a certain direction for the mechanism research of septic shock and stroke." (PMID 39655053, 2024). "Therefore, it is speculated that COX6C and NDUFB3 genes play an important role in the process of ischemia–hypoxia, neuronal apoptosis, and neuroinflammatory response in stroke." (PMID 39655053, 2024).
cancer (18 papers, 2015 to 2026). A tumor composed of atypical neoplastic, often pleomorphic cells that invade other tissues. "As a critical component of the mitochondrial inner respiratory chain, the heightened expression of COX6C is essential for the proliferation of malignant tumors." (PMID 40051782, 2025). "Through examining the genes localize on or nearby 8q22.1-22.2 region, we found a gene of mitochondrial electron transport chain, COX6C (Chr 8: 99,885,000-99,890,000), is frequently amplified in various cancers by TCGA data, including LUAD." (PMID 38242874, 2024). "Given the critical role of COX6C in regulating mitochondrial functions and cell proliferation, its abnormal expression probably closely correlates with clinical cancer progression." (PMID 38242874, 2024). "Another subunit of the cytochrome c oxidase, COX6C, also upregulated in relation to invasiveness in our study, appeared to be differentially expressed in various cancers." (PMID 37297007, 2023). "However, the mechanism of COX6C upregulation in cancers and its role in tumorigenesis remain elusive." (PMID 38242874, 2024). "Taken together, these data prove that COX6c is a crucial factor in the development of drug resistance in cancer cells and may be critical for the reasonable design and use of new treatment strategies to effectively confront cancers." (PMID 35879322, 2022). "Moreover, the protein composition, including cancer-associated markers such as MT-CO2, COX6c, SLC24A22, HLA-DR, and Erlin2, was highly consistent between EVs derived from fresh and frozen tissues, with no relevant enrichment of intracellular or mitochondrial contaminants in frozen-derived EVs." (PMID 42169004, 2026). "A disseminated cancer cell cluster with high levels of oxidative phosphorylation (OXPHOS), including the upregulation of cytochrome C oxidase subunit 6C and dehydrogenase/reductase 2, is identified." (PMID 36594618, 2023). "This duplication also recurrently affected known cancer census genes such as CSMD3, COX6C, EXT1, FAM135B, MYC, and NDRG1 in SG1 and SG3 in more than 75% of patients." (PMID 36129940, 2022).
tumor (14 papers, 2008 to 2025). "Consistent with previous results, COX6C is upregulated in most tumor tissues of LUAD patients (85/143, 59.44%)." (PMID 38242874, 2024). "In conclusion, we found that COX6C, a frequently amplified gene localizes to 8q22.1-22.2, is upregulated in tumor tissues and positively correlates with poorer prognosis of LUAD patients." (PMID 38242874, 2024). "Collectively, our results identified that COX6C exerts a positive role in regulating tumor proliferation both in vitro and in vivo." (PMID 38242874, 2024). "We further collected 40 paired LUAD tumor tissues and normal lung tissues, and compared with paired normal tissues, frequently elevated expression of COX6C was detected in tumor tissues by immunoblotting and qRT-PCR assays." (PMID 38242874, 2024). "Altogether, these data suggest the involvement of COX6c in gene rearrangement during tumorigenesis, providing additional tools for tumor diagnostics." (PMID 35879322, 2022). "Collectively, these observations suggest that COX6C contributes to tumor metabolism and may hold promise as a prognostic biomarker, though further clinical validation is required." (PMID 41157129, 2025). "In Cluster 10 (DCIS/LCIS), upregulated genes such as CPB1, COX6C, TFF3, and IL6ST reflect early-stage tumor characteristics and immune regulation." (PMID 41182757, 2025). "Several genes particularly CXCL14, COX6C, CRISP3, and MPG with high expression levels in these tumor regions were identified, while healthy cells exhibited few significant genes, with only MALAT1 observed." (PMID 39764614, 2024). "In addition, We found COX6C is frequently overexpressed in most of tumor tissues from LUAD patients, but the amplification of COX6C is only observed in about 4.1% LUAD patients according to TCGA data." (PMID 38242874, 2024). "COX6c, SLC25A22, and MT-CO2 – all of which are mitochondrial inner membrane proteins – were selected for validation and tested for their presence in tumour tissue, because they were relatively highly abundant in our samples, and less commonly identified in other EV proteomic studies." (PMID 31497264, 2019). "Our results were consistent with those of the meta-analysis such that GSN, SPTBN1, SFRP1 and MAF were down-regulated in most tumor samples with respect to their matched non-tumor samples whereas COX6C, RAD21, GSPT1, NME1 and PTTG1 were up-regulated." (PMID 19116033, 2008). "The fact that Mine and colleagues validated the COX6c/HMGIC translocation in uterine myomas suggested that the fusion partner COX6c gives rise to the detachment of the DNA-binding domains of HMGIC from the spacer and the acidic carboxyl-terminal regulatory domain, thereby promoting tumor growth." (PMID 35879322, 2022).
metabolic disease (2 papers, 2021 to 2024). A congenital disorder (due to inherited enzyme abnormality) or acquired (due to failure of a metabolically important organ) disorder resulting from an abnormal metabolic process. "Many studies have implicated a role for COX6C in metabolic diseases." (PMID 34714849, 2021). "It is therefore speculated that the COX6C and NDUFB3 genes may play an important role in the inflammatory response, oxidative stress, and metabolic disorders in septic shock." (PMID 39655053, 2024).
neurological diseases (2 papers, 2024 to 2025). "However, molecular effects through the associated competitive endogenous (ceRNA) of miR-140-3p-GPRIN1 axis of LINC02298, or through cytochrome c oxidase subunit 6C (COX6C) function, as found in other neurological diseases, may still be possible." (PMID 39338942, 2024). "These biomarkers represent critical molecular pathways involved in brain injury and neurological diseases, including transcriptional regulation (Sox TFs), neurotransmitter synthesis (DHPR), chromatin-related neurotoxicity and inflammation (Histone H1.5), and mitochondrial bioenergetics (COX6C)." (PMID 40663395, 2025).
brain disorder (1 paper, 2022). A disease affecting the brain or part of the brain. "Therefore, COX6c might represent a potential diagnostic biomarker or target molecule for brain disorders." (PMID 35879322, 2022).
cardiovascular disease (1 paper, 2022). "Furthermore, we summarized the elaborate roles that COX6c plays in various diseases, including cardiovascular disease, kidney disease, brain injury, skeletal muscle injury, and tumors." (PMID 35879322, 2022).
mitochondrial disease (1 paper, 2022). "Although mutations in COX6C have not been associated with human mitochondrial disease to date, defects in cype produce severe phenotypes in flies." (PMID 35663391, 2022).
COX6C also shares sentences with these, for which no sentence is quoted: diabetes (2 papers); gastric cancer (2); neurodegenerative disease (2); ovarian carcinoma (2); prostate tumor (2); thyroid cancer (2); uterine cancer (2); asthma (1); chronic kidney disease (1); endometriosis (1); follicular thyroid cancer (1); infection (1); invasive breast carcinoma (1); ischemic stroke (1); kidney disease (1); major depressive disorder (1); septicemia (1); thyroid tumor (1); viral infection (1).